IL1A (interleukin 1 alpha)
Description:
Cytokine constitutively present intracellularly in nearly all resting non-hematopoietic cells that plays an important role in inflammation and bridges the innate and adaptive immune systems. After binding to its receptor IL1R1 together with its accessory protein IL1RAP, forms the high affinity interleukin-1 receptor complex. Signaling involves the recruitment of adapter molecules such as MYD88, IRAK1 or IRAK4. In turn, mediates the activation of NF-kappa-B and the three MAPK pathways p38, p42/p44 and JNK pathways. Within the cell, acts as an alarmin and cell death results in its liberation in the extracellular space after disruption of the cell membrane to induce inflammation and alert the host to injury or damage. In addition to its role as a danger signal, which occurs when the cytokine is passively released by cell necrosis, directly senses DNA damage and acts as a signal for genotoxic stress without loss of cell integrity.
Synonyms: IL-1 alpha; IL1F1; IL-1A; IL1-ALPHA; IL1
Tractability: Antibody: a drug acting on it is in phase 2 or 3 trials; UniProt places it where antibodies can reach, with high confidence; its Gene Ontology location is reachable by antibodies, with high confidence.
Target class: Secreted protein
Gene: Protein-coding gene on chromosome 2 (112,773,925 to 112,784,493, reverse strand). Ensembl gene ENSG00000115008.
Subcellular location: Nucleus; Cytoplasm; Secreted
Subcellular location (Human Protein Atlas): Cytosol; Predicted to be secreted
Pathways (Reactome):
Immune System: Interleukin-1 processing; Interleukin-1 signaling; Interleukin-10 signaling; Interleukin-4 and Interleukin-13 signaling
Cellular responses to stimuli: Senescence-Associated Secretory Phenotype (SASP)
Disease: Purinergic signaling in leishmaniasis infection
Programmed Cell Death: Pyroptosis
Gene Ontology:
Molecular function: copper ion binding; cytokine activity; protein binding; interleukin-1 receptor binding
Biological process: cellular response to heat; cytokine-mediated signaling pathway; negative regulation of cell population proliferation; positive regulation of cytokine production; positive regulation of gene expression; positive regulation of interleukin-2 production; positive regulation of mitotic nuclear division; positive regulation of protein secretion; response to copper ion; apoptotic process; cellular response to lipopolysaccharide; immune response; inflammatory response; interleukin-1-mediated signaling pathway; monocyte differentiation; negative regulation of extrinsic apoptotic signaling pathway in absence of ligand; negative regulation of inflammatory response; negative regulation of interleukin-1 alpha production; negative regulation of interleukin-1-mediated signaling pathway; positive regulation of angiogenesis; positive regulation of canonical NF-kappaB signal transduction; positive regulation of immature T cell proliferation in thymus; positive regulation of inflammatory response; positive regulation of interleukin-6 production; positive regulation of MAPK cascade; and 5 more
Cellular component: cytoplasm; cytosol; extracellular region; nucleus; interleukin-1 receptor complex; plasma membrane
Genetic constraint (gnomAD): Loss-of-function variants: 8 observed, 15.65 expected, observed/expected ratio (o/e) 0.51, 90% interval 0.3 to 0.92. The upper end of that interval is the gene's LOEUF score, 0.92, which puts it in group 3 of 6, group 1 being the genes least tolerant of losing a copy. Missense variants: 294 observed, 312.16 expected, observed/expected ratio (o/e) 0.94, 90% interval 0.86 to 1.04. Synonymous variants: 108 observed, 118.33 expected, observed/expected ratio (o/e) 0.91, 90% interval 0.78 to 1.07.
Homologues: Orthologues: chimpanzee IL1A (100% identical), macaque IL1A (90% identical), pig IL1A (70% identical), dog IL1A (70% identical), rabbit IL1A (64% identical), rat Il1a (63% identical), mouse Il1a (61% identical), guinea pig IL1A (54% identical).
Diseases named in the same sentence as IL1A in open-access papers:
IL1A is named in the same sentence as 627 diseases in open-access papers, as found by Europe PMC text mining. Sharing a sentence is not in itself a finding about the gene and the disease. The quoted sentences say what the papers report.
COVID-19 (157 papers, 2020 to 2026). A disease caused by infection with severe acute respiratory syndrome coronavirus 2. "The SAVE-MORE RCT evaluated the efficacy and safety of anakinra, an IL-1α/β inhibitor, in 594 patients with COVID-19 at risk of progressing to respiratory failure (identified by plasma soluble urokinase plasminogen activator receptor serum levels)." (PMID 40333142, 2025). "Our study further investigated serum levels of CRP, IL-1α, IL-6, and IL-10 as predictive markers for identifying patients at risk of worsening COVID-19." (PMID 39338474, 2024). "While further limited by the small number of PLWH with severe illness, interaction models also suggested that higher concentrations of IFN-α2, IL-6, CCL3, IL-1a, and IL-1Ra were associated with more severe COVID-19 in PLWH." (PMID 38368384, 2024). "Antagonism of IL-1α/β by anakinra in COVID-19 patients at risk of developing respiratory failure showed clinical and short-term survival benefit." (PMID 37507425, 2023). "Several studies have reported that the use of anakinra, a dual blocker of IL-1α and IL-1β, in COVID-19 patients reduced the mortality risk, especially in the presence of signs of hyperinflammation." (PMID 37986089, 2023). "Specific genetic mutations of IL-1α were investigated in another review study and found to increase the severity of COVID-19." (PMID 37568161, 2023). "For example, the recent SAVE-MORE trial showed that anakinra, which blocks both IL-1α and IL-1β, reduced the risk of clinical progression in patients with COVID-19, when co-administered with dexamethasone." (PMID 36505497, 2022). "The “SAVE-MORE” study evaluated the safety and efficacy of Anakinra, an IL-1α/β inhibitor, in a large cohort of COVID-19 patients at risk of progression to respiratory failure, with a level of suPAR ≥ 6 ng/mL." (PMID 36556207, 2022). "Consistent with published studies, we observed high concentrations of inflammation-associated cytokines, including IL-6, TNF-α, IP-10, IL-10, IL-1α and IL-1β, in serum and nasal lining fluid from PCR-confirmed COVID-19 patients." (PMID 34117221, 2021). "In severe COVID-19, the expression of IL-1α, IL-1β, and IL-1 receptor and their associated downstream signaling molecules were induced before respiratory function worsened." (PMID 34176095, 2021). "A surprising finding in our analysis was the association of decreased longitudinal trajectories of IL-1α with increased risk of death in COVID-19 patients." (PMID 33232303, 2021). "HGF, IL-1α, and IL 27 at hospital admission were strongly associated with severe/critical COVID-19 patients and therefore are excellent predictors of bad prognosis." (PMID 34066892, 2021). "SARS-CoV-2 infection elicited an innate immune response in this human alveolus MPS with significant increase in IP-10, a chemoattractant for monocytes, TRAIL which induces apoptosis and to some extent IL-1α, a strong inflammatory cytokine associated with severe COVID-19 cases." (PMID 39697363, 2024). "However, the brain inflammation associated with COVID-19 increases the concentration of cytokines that negatively affect adult human neurogenesis, e.g., IL-6, IL-1β, IL-1α, and TNF." (PMID 36672177, 2023). "The SAVE-MORE double-blind, randomized controlled trial evaluated the efficacy and safety of anakinra, an IL-1α/β inhibitor, in 594 patients with COVID-19 at risk of progressing to respiratory failure as identified by plasma suPAR ≥6 ng ml−1, 85.9% (n = 510) of whom were receiving dexamethasone." (PMID 34480127, 2021). "This shows that the expression of IL-1α, IL-1β, and its signaling pathway molecules increase within 3-5 days post disease onset and might be positively associated with poor prognosis of COVID-19." (PMID 35126355, 2021). "It remains elusive how decreased levels of IL-1α, a danger-associated molecular pattern typically released from injured epithelial cells, might heighten the risk of death during COVID-19." (PMID 33232303, 2021).
COVID-19 (continued). "Another possibility is related to the endotheliopathy associated with COVID-19 and the release of IL-1α, which may be inhibited by anakinra." (PMID 34803441, 2021). "Besides, lytic death of epithelial and endothelial cells in the lung following COVID-19 causes a massive release of IL1-α, which is mainly involved in local microenvironment inflammation." (PMID 34715834, 2021). "In addition to high early IFN responses, moderate COVID-19 is associated with increased plasma levels of a core of pro-inflammatory cytokines, chemokines and growth factors (e.g., IL-1a, IL-1β, IFNα, IL-12p70, and IL-17A) that are effectively resolved during infection." (PMID 37491352, 2023). "CBD was also shown to reduce interleukin (IL)-2, IL-1α and β, interferon gamma, inducible protein-10, monocyte chemoattractant protein-1, macrophage inflammatory protein-1α, and tumor necrosis factor-α – all of which are associated with the pathology of severe cases of COVID-19." (PMID 36844029, 2023). "Using the data presented here on IgM SARS-CoV-2 peptide reactivity and serum cytokine levels of IL-1α, IL-6, and IL-18, we have identified a unique biomarker panel which could be used for early identification of COVID-19 patients with increased risk of severe and potentially fatal disease." (PMID 35386707, 2022). "Serum from patients with severe COVID-19 induced increased levels of IL-1α, IL-1Ra, IL-5, IL-6, IL-10, IL-12(p40), IL-18, IL-27, and TNF-α." (PMID 41583455, 2025). "This is because IL-1α, IL-1β, IL-5, IL-8, NF-κβ, and interferons (α, β, and γ), are molecules that overlap with the immune response to COVID-19." (PMID 39941142, 2025). "IL-1α-mediated inflammation likely contributes to the pathogenesis of COVID-19, leading to various pathological alterations through the activation of inflammatory cascades, myeloid cell sensing, and inflammasome activation." (PMID 40149530, 2025). "This study demonstrated the efficacy of anakinra, an IL-1α/β inhibitor, in patients with COVID-19 and high serum levels of soluble plasminogen activator receptor." (PMID 40333142, 2025). "It is plausible that, in addition to the corticoid response, IL-1α influences the response to the immunomodulators used to reduce the cytokine storm in COVID-19 patients." (PMID 40149530, 2025). "In the individuals with severe COVID-19, we found that the autoantibody levels of IL-1α, IFNα2, TNFα, osteopontin, and IFNβ showed a high correlation with each other." (PMID 38491326, 2024). "The mRNA-LNP COVID-19 vaccine can activate complements and increase the production of proinflammatory cytokines including IL-1α, IL-1β, IL-6, IL-8, IFN-γ, and TNF-α in PBMC cultures." (PMID 39852793, 2024). "COVID-19 severity was associated with immune suppression, overexpression of proinflammatory cytokines, including CRNN, IL1A, S100A7, and IL23A, and activation of pathways involved in keratinocyte proliferation." (PMID 38375062, 2024). "Pronounced expression of complement proteins (C1q, C3, C3b, C4, C5) and inflammatory cytokines (TNF, IL-1α, and IL-17A/E) was detected in the fetal compartment of COVID-19-affected pregnancies." (PMID 39390219, 2024). "In the severe COVID-19 group, levels of autoantibodies against IL-1α, IFNα2, TNFα, osteopontin and IFNβ all showed high correlation." (PMID 38491326, 2024). "Taken together, we found that COVID-19 severity in the Ghanaian cohort was associated with dysregulated inflammatory response mediated by MAL, IL1A, IL23A, CRNN, and S100A7 overexpression and suppression of antiviral immune response-related pathways." (PMID 38375062, 2024). "Fractalkine has been found to positively correlate with Eotaxin and IL-1A in patients with COVID-19." (PMID 38793604, 2024). "Analysis of the GEO database revealed elevated expression levels of pro-inflammatory cytokine genes, including interleukin-1α (IL-1A), IL-1β, and IL-6, in individuals with severe COVID-19 compared to healthy controls." (PMID 39519351, 2024).
COVID-19 (continued). "Intriguingly, in our current study, it has a negative correlation with several cytokines in healthy control, but with only IL-1α and IL-33 in COVID-19 patients, denoting the variable response to SARS-CoV-2 infection in different ethnicities." (PMID 38855114, 2024). "In the severe COVID-19 group, we observed a hyperinflammatory state, as judged by increased concentration of cytokines (IL-1α, IL-4, IL-6, IL-10 and IL-17A), chemokines (IP-10 and MIP-1β), and adhesion markers (E-selectin and ICAM-1)." (PMID 37441066, 2023). "We found that, at the time of treatment initiation, COVID-19 patients who responded to tocilizumab had higher levels of several pro-inflammatory cytokines, including IL-1β, IL-1α and IFN-β." (PMID 37215114, 2023). "The alarmin IL-1α was found to be downregulated only in pregnant COVID-19 cases, although a tendency towards the same reduction was observed in non-pregnant patients." (PMID 37016066, 2023). "Convalescent COVID-19 children had elevated levels of IFNγ, IL-2, TNFα, IL-1α, IL-1β, IFNα, IFNβ, IL-6, IL-12, IL-17A, IL-10 and G-CSF in comparison to control children." (PMID 37013538, 2023). "Acute COVID-19 children had significantly elevated levels of cytokines, IFNγ, IL-2, TNFα, IL-1α, IL-1β and IFNα in comparison to convalescent children." (PMID 37013538, 2023). "Convalescent COVID-19 children had elevated levels of IFNγ, IL-2, TNFα, IL-1α, IL-1β, IFNα, IFNβ, IL-6, IL-12, IL-17A and G-CSF in comparison to control children." (PMID 37013538, 2023). "With COVID-19 being characterized by hypercoagulability, IL-1α can play a contributory role to coagulation phenomena too- by itself getting thrombin activated and inducing platelet productions." (PMID 35431536, 2022). "A third module (c) revolves around TNF and includes IL1A, IL1B, TNFSF14, TNFAIP3, and CSF2 that likely mediates the inflammatory response associated with COVID-19 progression." (PMID 35085325, 2022). "They observed a “key COVID-19 feature” shared by the moderate and severe disease groups, which they defined as the following inflammatory cytokines: IL-1α, IL-1β, IL-17A, IL-12 p70, and IFNα." (PMID 35774397, 2022). "IL-1α, IL-1β and ferritin were relatively increased in patients with COVID-19, particularly when compared with CAP-other and CAP-flu, whilst procalcitonin, IL-6 and CRP were highest in CAP-strep." (PMID 35660785, 2022). "Increased IL-1α and IL-1β expression was revealed in severe COVID-19 patients prior to development of respiratory distress." (PMID 36422492, 2022). "In agreement with previous studies, we found that severe COVID-19 patients had elevated serum levels of IL-1α, IL-1β IL-6 and IL-18." (PMID 36142255, 2022). "Pro-inflammatory cytokines IL-6, TNF-α, IL-8, IL-1α, anti-inflammatory cytokine IL-4, and the IP-10 chemokine were induced in the severe presentation of COVID-19 during pregnancy." (PMID 36016660, 2022). "Specifically, ncfDNA was correlated with cytokines/chemokines such as IL-15, IL-8, Eotaxin-3, IL-1β, IL-10, IL-16, VEGF, IL-6, IL-7, GM-CSF and IL-1α in SOTRs with COVID-19." (PMID 35075453, 2022). "IL-1α plays a central role in the pathogenesis of ARDS in COVID-19: the release of IL-1α after the damage of the lung epithelium results in myeloid cell recruitment and inflammasome activation, leading to amplification of the inflammatory cascade." (PMID 35741174, 2022). "PC2 separated COVID-19 patients from other forms of CAP due to elevated levels of IL-1α and IL-1β (PC2 scores for COVID-19 versus both other groups P<0·001, not significant between CAP-flu and CAP-strep)." (PMID 35660785, 2022). "The results showed that the level of pro-inflammatory cytokines, TNF-α, IL-6, IL-8, and IL-1β were significantly elevated in severe COVID-19 patients, but the alarmin molecules IL-1α and HMGB1 were marginally higher." (PMID 36585712, 2022). "In family n°12, also the p.Gln11Leu in TLR7 and p.Ala114Ser in IL1A co-segregated with COVID-19 positive status." (PMID 36228008, 2022).